STAT5B (signal transducer and activator of transcription 5B)
Diseases named in the same sentence as STAT5B in open-access papers (continued):
Sharing a sentence is not in itself a finding about the gene and the disease.
hypereosinophilic syndrome (3 papers, 2019 to 2025). Hypereosinophilic syndrome (HES) constitutes a rare and heterogeneous group of disorders, defined as persistent and marked blood eosinophilia and/or tissue eosinophilia associated with a wide range of clinical manifestations reflecting eosinophil-induced tissue/organ damage. "STAT5B acts downstream of JAK1, a gene in which gain-of-function mutations reportedly cause hypereosinophilic syndrome, and it is the target of the approved AD therapeutic agent baricitinib." (PMID 41357518, 2025). "A working diagnosis of idiopathic hypereosinophilic syndrome (HES) had been made in 7 cases prior to the finding of STAT5B N642H and CEL-NOS in 2 cases, supported by the finding of an additional chromosome 8 by cytogenetic analysis in both cases." (PMID 30573779, 2019).
lymphoid tumor (3 papers, 2014 to 2019). "To dissect the individual contribution of STAT5A and STAT5B to lymphoid tumor formation, we injected Stat5a−/−, Stat5b−/−, or wt BCR/ABLp185+ cell lines subcutaneously into NSG mice." (PMID 30679796, 2019). "Moreover, in several lymphoid tumors cell lines, constitutive phosphorylation of a newly identified cytokine-inducible Ser193 site within human STAT5b was found, supporting the possible involvement of serine phosphorylation in cancer cells." (PMID 24489959, 2014).
mantle cell lymphoma (3 papers, 2023 to 2025). Mantle cell lymphoma is a rare form of malignant non-Hodgkin lymphoma affecting B lymphocytes in the lymph nodes in a region called the ``mantle zone''. "Signal transducer and activator of transcription 5B(STAT5B) has been identified as a positive regulator of ferroptosis in mantle cell lymphoma (MCL), which is upregulated and acts as a positive regulator of ferroptosis escape in MCL." (PMID 41462004, 2025).
mastitis (3 papers, 2020 to 2023). Inflammation of breast tissue during lactation or postpartum due to an obstructed duct or infection. "Polymorphisms in CD4 and STAT5B genes and their link with mastitis resistance phenotypic traits have been well studied." (PMID 36911690, 2023). "A few studies noticed a significant association of polymorphism in the STAT5A and STAT5B genes with mastitis resistance phenotypic traits." (PMID 36911690, 2023). "In the previous study, it was noticed that polymorphisms in CD4 and STAT5B genes are significantly linked with mastitis-resistance phenotypic traits." (PMID 33202860, 2020). "Similarly, mutation at point 43673888A>G in the STAT5B gene was significantly linked to mastitis-resistance phenotypic traits (IL-4 and SCC)." (PMID 33202860, 2020). "Furthermore, it is suggested that the interactive mechanism of SOCS3, STATs, and JAK2, STAT5A, and STAT5B during milk production and mastitis development should be considered in future rodent-knockout research models." (PMID 33202860, 2020).
non-small cell lung carcinoma (3 papers, 2014 to 2023). A group of at least three distinct histological types of lung cancer, including non-small cell squamous cell carcinoma, adenocarcinoma, and large cell carcinoma. "SGK1, identified in our study as a target gene of both STAT5A and STAT5B, has also been implicated in the pathophysiology of non-small-cell lung cancer and adrenocortical tumors in humans, although this has not been reported in rodents." (PMID 24497979, 2014).
oral cancer (3 papers, 2015 to 2022). "In another study, it is reported that there are about 14 essential genes involved in oral cancer genesis from leukoplakia, including Signal Transducer and Activator of Transcription 5B (STAT5B) and Epidermal Growth Factor Receptor (EGFR), and eight miRs, such as miR-549, miR-205, and miR-21." (PMID 34946938, 2021).
steatosis (3 papers, 2016 to 2021). Increased lipid within the cytoplasm of cells. "In addition, GWAS data collected from patients with NAFLD revealed single nucleotide polymorphisms (SNPs) in 18 different genes in the GH signaling pathway, including Gh, Ghr, Jak2, and Stat5b, are associated with steatosis." (PMID 34685512, 2021). "Given the relationship between suppression of STAT5b function and liver steatosis (see Introduction), it is conceivable that many of the chemical treatments examined in these biosets lead to steatosis." (PMID 26959237, 2016). "The increase in steatosis seen in STAT5b-null mice is hypothesized to occur through the activation of transcription factors that regulate triglyceride or cholesterol homeostasis." (PMID 26959237, 2016). "The relationship between feminization and increased expression of Pparg may provide a plausible explanation for increased steatosis in biosets in which there are decreases in STAT5b activity, similar to increases in steatosis in mice that lack a functional STAT5b." (PMID 26959237, 2016).
B-cell lymphoma (2 papers, 2013 to 2025). "STAT5A is frequently implicated in oncogenic processes, particularly in breast and hematologic cancers, whereas STAT5B more consistently associates with favorable survival outcomes in epithelial tumors and B-cell lymphomas." (PMID 41301421, 2025). "High STAT5B expression was most strongly associated with improved survival in lung adenocarcinomas and B-cell lymphomas, suggesting unique mechanisms by which STAT5B constrains malignant progression." (PMID 41301421, 2025). "In B-cell lymphoma, patients with high STAT5B expression showed markedly prolonged survival compared to those with low expression." (PMID 41301421, 2025). "Interestingly, similar observations were made in mice that over-express a constitutively active Stat5b transgene and develop B cell lymphoma but not in the B6 transgenic mice with the same non-activated form of Stat5b." (PMID 23457589, 2013).
breast tumor (2 papers, 2008 to 2012). "Collectively, these experimental data indicate distinct roles of Stat5a and Stat5b in breast tumor biology." (PMID 23036105, 2012).
chronic lung disease (2 papers, 2013 to 2024). According to the definitions of the American and British Thoracic Societies, including pulmonary functional tests, X-rays, and CT scans for items such as fibrosis, bronchiectasis, bullae, emphysema, nodular or lymphomatous abnormalities. "These patients also exhibited a reduction in the numbers of regulatory T cells, suggesting that loss of STAT5B in humans appears to be sufficient for the initiation of certain immune phenotypes as well as chronic lung disease." (PMID 23565285, 2013).
Cognitive impairment (2 papers, 2022 to 2024). Abnormal cognition is characterized by deficits in thinking, reasoning, or remembering. "Most importantly, plasma APOE, MMP9, S100A8, UBR5 PLA2G7, and STAT5B play a potentially crucial role in the progression of cognitive disorders." (PMID 38883967, 2024).
diabetic nephropathy (2 papers, 2012 to 2023). "Interestingly, higher expression of the Stat5B in progressive diabetic nephropathy patients has been shown." (PMID 22615750, 2012).
diffuse large B-cell lymphoma (2 papers, 2021 to 2025). "The protective association of high STAT5B expression was particularly strong in hematologic malignancies, especially in diffuse large B-cell lymphoma." (PMID 41301421, 2025). "The particularly favorable impact in diffuse large B-cell lymphoma (DLBCL) may reflect STAT5B’s role in preserving B-cell differentiation programs or counteracting oncogenic pathways." (PMID 41301421, 2025).
dwarfism (2 papers, 2023 to 2024). "Lastly, Tmem263-KO male mouse liver DEGs were compared to those of Stat5b-KO male mice, which exhibit dwarfism and GH pulse resistance." (PMID 38241182, 2024). "Delayed puberty is found in humans with Laron dwarfism who are insensitive to GH due to a mutation in GHR or STAT5b (a signal transducer and activator of transcription 5b) genes." (PMID 37064267, 2023).
enteropathy-associated T-cell lymphoma (2 papers, 2021 to 2024). An uncommon mature T-cell lymphoma of intraepithelial lymphocytes. "The STAT5B p.N642H gain-of-function mutation, as well as other SH2 domain mutations, were identified in CTCL, NKCL, LGL, enteropathy-associated T cell lymphoma and γδ T cell lymphoma and, like in ALL, resulted in increased STAT5B phosphorylation and transcriptional activity." (PMID 34066732, 2021).
fatty liver (2 papers, 2016 to 2024). "Given the relationships between suppression of hepatic STAT5b function and disruption of lipid homeostasis, we hypothesize that a subset of these chemicals cause effects in the liver, including fatty liver disease and hepatocarcinogenesis, in part through the suppression of STAT5b function." (PMID 26959237, 2016).
Hyperglycemia (2 papers, 2021 to 2025). An increased concentration of glucose in the blood. "Studies have shown the ability of NTS to enhance growth hormone signaling via the JAK2/STAT5b/IGF-1 axis and to produce anti-inflammatory effects against hyperglycemia in human monocytes." (PMID 34068523, 2021).
Infertility (2 papers, 2024 to 2025). "Specific study of the contribution of STAT5B to this process has been hampered by the infertility of the corresponding knockout mice." (PMID 40163145, 2025). "Specific study of the contribution of STAT5B to this process has been hampered by the infertility of STAT5B knockout mice." (PMID 38903072, 2024). "While investigations utilizing mouse genetics have shed light on the modulatory role of STAT5A in mammary alveolar differentiation, understanding the precise contribution of STAT5B in mammary gland development is unclear due to the infertility of Stat5b-null mice, preventing direct investigation." (PMID 40163145, 2025).
invasive breast carcinoma (2 papers, 2012 to 2023). A carcinoma that infiltrates the breast parenchyma. "Unexpectedly, the analyses revealed frequent and selective loss of nuclear as well as total Stat5a protein in invasive breast cancer and lymph node metastases, whereas expression of Stat5b remained unchanged." (PMID 23036105, 2012). "Tumor levels of Stat5a and Stat5b mRNA in a cohort of 936 patients with available outcome data were then interrogated to determine whether expression of Stat5a or Stat5b in primary invasive breast cancer was associated with clinical outcome." (PMID 23036105, 2012). "Thus, STAT5A and STAT5B may help to detect invasive breast cancer patients." (PMID 36862902, 2023).
IPEX syndrome (2 papers, 2021 to 2022). "Here, HIES including STAT3 deficiency and STAT3-related deficiency is also associated with activated Th2 responses and decreased Th17 generations; CARD11 deficiency, IPEX syndrome, STAT5B deficiency, and OS affect Treg diversity or function that regulates Th2 immunity." (PMID 36140582, 2022).
liver fibrosis (2 papers, 2019 to 2026). "Analysis of hepatic transcriptional profiles of MCD and GNMTKO mice reveals novel association of the transcriptional regulators STAT5b, AhR, and ARNT with liver fibrosis." (PMID 41519232, 2026). "Our results showed that TP supplementation alleviated liver morphology, liver function and liver fibrosis; improved oxidative stress parameters; and increased the expression of STAT5b, Nrf2, HO-1 and NQO-1 and decreased the expression of Keap1 in the liver tissues of aged rats." (PMID 31819135, 2019).
lymphopenia (2 papers, 2012 to 2016). Reduction in the number of lymphocytes. "Prior studies on STAT5b deficient subjects have revealed immunological aberrations associated with the following disease phenotype: modest lymphopenia and decreased populations of Treg, γ−δ T cells, and natural killer (NK) cells." (PMID 22912632, 2012). "Immune repertoires of STAT5b deficient patients have shown moderate lymphopenia, with very low numbers of NK and T cells, as well as Treg dysfunction." (PMID 22912632, 2012). "The STAT5b deficient patient had moderate T cell lymphopenia, normal CD4/CD8 ratios, and very low numbers of NK cells and γ−δ T cells, and the T cells presented a chronically hyperactivated phenotype." (PMID 22912632, 2012).
neuroblastoma (2 papers, 2023). Neuroblastoma (NB) is the most common solid, extracranial childhood tumor. "In neuroblastoma cell lines, STAT5B has been reported as a target of 5-aza-2′-deoxycytidine treatment to induce cell apoptosis and inhibit cell proliferation by changing the expression level of genes involved in the JAK/STAT pathway, indicating its important role." (PMID 37835497, 2023). "In addition, in neuroblastoma (z score = 2.46, p = 0.0138) and triple negative breast cancer (z score = 1.99, p = 0.0471), escalated CTL levels suggested more favorable prognosis when STAT5B had relatively low expression." (PMID 36968603, 2023).
NK cell leukemia (2 papers, 2020 to 2022). "Provided that IL-15 is an upstream factor of STAT5b and that IL-15 transgenic mice develops the aggressive variant of T or NK cell leukemia, the IL-15-STAT5 axis might be considered crucial for neoplastic transformation." (PMID 32133291, 2020).
severe combined immunodeficiency (2 papers, 2022 to 2023). Severe combined immunodeficiency (SCID) comprises a group of rare monogenic primary immunodeficiency disorders characterized by a lack of functional peripheral T lymphocytes resulting in early-onset severe respiratory infections and failure to thrive. "Examples include severe combined immunodeficiency (SCID) and STAT5B deficiency affecting T cells and NK cells with impaired interferon (IFN) α responses." (PMID 37632006, 2023). "Such diseases include CD25 or IL-2RA deficiency, mutations within STAT5b, STAT1 or STAT3, Dedicator of Cytokinesis 8 (DOCK8) deficiency as well as infantile or eosinophilic enteropathies and severe combined immunodeficiency (SCID)." (PMID 35207219, 2022).
acquired aplastic anemia (1 paper, 2015). Acquired aplastic anemia is a rare, serious blood disorder, due to failure of the bone marrow to produce blood cells. "STAT5B N642H mutation has also been observed in acquired aplastic anemia." (PMID 26536348, 2015).
AIDS (1 paper, 2025). A syndrome resulting from the acquired deficiency of cellular immunity caused by the human immunodeficiency virus (HIV). "HIV also frequently integrates into lymphocyte activation genes, such as CD5, IL7R, STAT5B, TNFAIP3, and MALT1, which are actively transcribed during immune activation, with higher integration rates in the AIDS group." (PMID 39788938, 2025).
Anxiety (1 paper, 2025). Intense feelings of nervousness, tension, or panic often arise in response to interpersonal stresses. "STAT5B knockout mice exhibit significantly reduced brain dopamine levels, increased dopaminergic neuron mortality, and abnormal behaviors, including decreased locomotor activity and anxiety." (PMID 40801579, 2025).
atherosclerosis (1 paper, 2023). A disease characterized by the build-up of fatty material and calcium deposition in the arterial wall resulting in partial or complete occlusion of the arterial lumen. "Next, we examined the expression of STAT5A and STAT5B isoforms in human atherosclerosis." (PMID 37920458, 2023).
brain cancer (1 paper, 2025). A primary or metastatic malignant neoplasm affecting the brain. "For example, miR-128 plays a crucial role in nervous system development by targeting Forkhead Box M1, cAMP response element-binding protein (CREB), splicing factor SC35, and LIM domain kinase 1 (Limk1), and has also been linked to various types of brain cancer via targeting STAT5B and KRAS genes." (PMID 40563979, 2025).
central obesity (1 paper, 2023). "Several patients harbouring STAT5B LOF mutations also displayed central obesity, while those with acquired GH deficiency possess increased visceral and abdominal fat mass in particular." (PMID 36995466, 2023).
chronic eosinophilic leukemia (1 paper, 2019). "The overall survival of STAT5B-mutated HES cases was only 30 months, suggesting that these cases should be reclassified as chronic eosinophilic leukemia, not otherwise specified (CEL-NOS)." (PMID 30573779, 2019).
colorectal tumors (1 paper, 2025). "The pronounced reduction in STAT5B expression in multiple epithelial-derived cancers, including breast, lung, and colorectal tumors, suggests a role in maintaining epithelial homeostasis and suppressing malignant transformation." (PMID 41301421, 2025).
crescentic glomerulonephritis (1 paper, 2025). A histopathologic term for a pattern of diseases characterized by extensive crescent formation in the glomeruli; patients present clinically with rapid deterioration of renal function, and possible progression to end-stage renal failure within weeks or months. "In short, we report a unique case diagnosed with crescentic glomerulonephritis associated with NK-LGLL, with pathogenic N642H mutation in STAT5B, Epstein-Barr virus infection and poor prognosis, different from typical inert type." (PMID 40629603, 2025).
cutaneous T-cell lymphomas (1 paper, 2017). "Acquired mutations were recently described in cutaneous T-cell lymphomas for the JAK1, JAK3, STAT3, and STAT5B genes of the JAK-STAT pathway." (PMID 29262599, 2017).
diabetic cardiomyopathy (1 paper, 2024). Diabetic cardiomyopathy is a disorder of the heart muscle in people with diabetes. "Through exploration of the transcription factors, we identified Tcf21, Arnt, Stat5a, and Stat5b as potentially key players in the development of diabetic cardiomyopathy, particularly in regulating endothelial cells and myocardial cells." (PMID 38664790, 2024).
diffuse astrocytoma (1 paper, 2021). A low-grade (WHO grade II) astrocytic neoplasm. "A study that contained nine normal cortex, 22 diffuse astrocytoma, and 15 GBM samples showed that high levels of STAT5B were detected in 57.1% of GBM samples, 27.3% of diffuse astrocytoma samples, and 22.2% of normal cortex samples." (PMID 34276757, 2021).
EBV infection (1 paper, 2025). "EBV infection and the pathogenic N642H mutation in STAT5B were identified in this case, suggesting that STAT5B inhibitors may be a novel therapeutic strategy." (PMID 40629603, 2025). "Intriguingly, N642H mutation of STAT5B and EBV infection were also detected in this patient." (PMID 40629603, 2025).
gastric adenocarcinoma (1 paper, 2020). "Additionally, Notch1 had a positive correlation with CD4, GATA3 and STAT5B and a negative correlation with CD59 in gastric adenocarcinoma." (PMID 32028262, 2020).
Hepatosplenomegaly (1 paper, 2018). Simultaneous enlargement of the liver and spleen. "The majority of LRBA patients (75%) also developed lymphoadenopathy and/or hepatosplenomegaly, whereas serious viral and bacterial infections seem to cluster mainly in subjects with mutations in CD25, STAT1GOF, and STAT5b mutated subjects." (PMID 30443250, 2018).
infarction (1 paper, 2024). A localised pathological necrosis of tissue resulting from obstruction of the blood supply usually by a thrombus, an embolus, or vascular torsion. "BMSC-Exos lncRNA KLF3-AS1 regulates the miR-23c/signal transducer and activator of transcription 5B (STAT5B) axis, which promotes the secretion of IGF-1 by MSCs, reduces infarction size and apoptosis, thereby protecting the damaged myocardium." (PMID 39350967, 2024).
ischemic cardiomyopathy (1 paper, 2025). Ischemic cardiomyopathy is a cardiomyopathy in which a weakness in the muscle of the heart due to inadequate oxygen delivery to the myocardium with coronary artery disease being the most common cause. "In a previous study, it was discovered that SNRPA in ischemic cardiomyopathy (ICM) directly binds to the 3′UTR of STAT5B and promotes its substitution for polyadenylation, a process that is coordinated with alternative splicing (AS)." (PMID 41477636, 2025).
leiomyoma (1 paper, 2007). A well-circumscribed benign smooth muscle neoplasm characterized by the presence of spindle cells with cigar-shaped nuclei, interlacing fascicles, and a whorled pattern. "They included several genes such as NR2F1, PNN, Smad4, Smad5, STAT5B, JUN, TGIF2, and ATF1 that were over-expressed while RUNX3, STAT1, STAT6, EGR3, GAS7, Smad1, and EDF1 were underexpressed in leiomyomas as compared to keloid/incisional scars." (PMID 17718906, 2007).